CLEC3B (C-type lectin domain family 3 member B)
Description:
Tetranectin binds to plasminogen and to isolated kringle 4. May be involved in the packaging of molecules destined for exocytosis. Plays a role in retinal function.
Synonyms: TN; TNA; MCDR4
Tractability: Small molecule: it has a high-quality binding pocket. Antibody: its Gene Ontology location is reachable by antibodies, with high confidence; UniProt places it where antibodies can reach, with medium confidence; UniProt predicts a signal peptide or a membrane-spanning region.
Gene: Protein-coding gene on chromosome 3 (45,001,548 to 45,036,071, forward strand). Ensembl gene ENSG00000163815.
Subcellular location: Secreted
Pathways (Reactome):
Hemostasis: Platelet degranulation
Gene Ontology:
Molecular function: calcium ion binding; heparin binding; kringle domain binding
Biological process: bone mineralization; ossification; positive regulation of plasminogen activation
Cellular component: cytoplasm; extracellular exosome; extracellular matrix; extracellular region; granular component; platelet dense granule lumen
Genetic constraint (gnomAD): Loss-of-function variants: 15 observed, 16.83 expected, observed/expected ratio (o/e) 0.89, 90% interval 0.6 to 1.37. The upper end of that interval is the gene's LOEUF score, 1.37, which puts it in group 5 of 6, group 1 being the genes least tolerant of losing a copy. Missense variants: 240 observed, 268.28 expected, observed/expected ratio (o/e) 0.89, 90% interval 0.8 to 1. Synonymous variants: 112 observed, 116 expected, observed/expected ratio (o/e) 0.97, 90% interval 0.83 to 1.13.
Homologues: Orthologues: chimpanzee CLEC3B (100% identical), macaque CLEC3B (97% identical), dog CLEC3B (85% identical), pig CLEC3B (85% identical), mouse Clec3b (79% identical), guinea pig CLEC3B (66% identical), tropical clawed frog clec3b (56% identical), zebrafish clec3ba (53% identical), zebrafish clec3bb (49% identical). Paralogues in human: CLEC3A (45% identical), CLEC11A (30% identical).
Diseases named in the same sentence as CLEC3B in open-access papers:
CLEC3B is named in the same sentence as 64 diseases in open-access papers, as found by Europe PMC text mining. Sharing a sentence is not in itself a finding about the gene and the disease. The quoted sentences say what the papers report.
lung carcinoma (20 papers, 2020 to 2025). "Our findings indicate that CLEC3B expression is downregulated in lung cancer and reveal the diagnostic and prognostic potential of CLEC3B in lung cancer and its potential as an immune-related therapeutic target in lung cancer." (PMID 32265595, 2020). "In the present study, we observed a decrease in CLEC3B expression in lung cancer, which was associated with worse OS and DFS." (PMID 32265595, 2020). "Specifically, CLEC3B is significantly downregulated in stage IA lung cancer patients (p < 0.001) and has a high diagnostic accuracy (area under the receiver operating characteristic curve > 0.9)." (PMID 32265595, 2020). "We hypothesize that CLEC3B may serve as a potential diagnostic and prognostic biomarker and novel immune-related therapeutic target for lung cancer." (PMID 32265595, 2020). "Thus, we reported that CLEC3B is related to lung cancer and identified a possible potential diagnostic and prognostic biomarker and immune-related therapeutic target for lung cancer." (PMID 32265595, 2020). "The GEO and TCGA datasets were used to evaluate the diagnostic potential of CLEC3B in lung cancer." (PMID 32265595, 2020). "Multivariate analysis value showed that low expression of CLEC3B may be an independent risk factor for disease‐free survival in lung cancer patients (HR = 0.655, 95% CI 0.430–0.996, Cox p = 0.048)." (PMID 32265595, 2020). "In conclusion, we found that CLEC3B is downregulated in lung cancer, and it may act as an early stage diagnostic marker in lung cancer patients." (PMID 32265595, 2020). "Moreover, low expression of CLEC3B is related to poor progression-free survival (HR = 0.60, 95% CI 0.49–0.74, p = 8.3e−07) and overall survival (HR = 0.66, 95% CI 0.58–0.75, p = 2.1e−10), indicating it as a risk factor for lung cancer." (PMID 32265595, 2020). "In addition, low expression of CLEC3B is associated with poor prognosis in lung cancer." (PMID 32265595, 2020). "Therefore, the lower expression of CLEC3B may be defined as an independent risk factor for DFS in lung cancer patients." (PMID 32265595, 2020). "In addition, we also investigated the potential role of CLEC3B in tumor-immune interactions and found that CLEC3B might be associated with the immune infiltration and immune activation of lung cancer, especially in squamous cell carcinoma." (PMID 32265595, 2020). "There was a strong correlation between the survival time of individuals with lung cancer and 7 genes (CLEC3B, AOC3, HBB, CAT, SEPP1, FGA, and ORM1, P<0.05)." (PMID 40496615, 2025). "In lung cancer, CLEC3B expression is also reduced, and low expression of CLEC3B is an independent risk factor for disease-free survival." (PMID 39553729, 2024). "CLEC3B and CD302 have been verified downregulated in lung cancer and having the diagnostic and prognostic values in lung cancer." (PMID 37325647, 2023). "CLEC3B regulates immune infiltrating cells and since its regulation occurs at the early stages of lung cancer, it was suggested that it plays an important role in early prognosis." (PMID 36067196, 2022). "The results showed the difference in protein expression of the hub genes (GRIA1 and CLEC3B) in normal and lung cancer tissues." (PMID 35936688, 2022). "It is reported that CLEC3B is downregulated in lung cancer and involved in immune activation and proliferation inhibition." (PMID 36232952, 2022). "CLEC3B is also downregulated in many lung cancer types (adenocarcinoma, squamous cell carcinoma, and large cell carcinoma) and its expression is correlated with the inhibition of LC proliferation." (PMID 36067196, 2022). "While functioning as tumor suppresser in lung cancer, expression of CLEC3B was proved to be related to a poor prognosis in colorectal cancer and gastric cancer." (PMID 34513664, 2021). "A previous study demonstrated that the expression of CLEC3B is correlated with the level of immune infiltration in lung cancer, and it is promising to be the important marker for the early diagnosis of lung cancer." (PMID 34416861, 2021).
lung carcinoma (continued). "A paired t-test of H-scores revealed that the downregulation of CLEC3B in lung cancer was significant (P < 0.001)." (PMID 32265595, 2020). "Other significant findings of the present study are that CLEC3B plays a role in tumor-immune interactions and that CLEC3B expression is correlated with the immune infiltration level in lung cancer, especially in SCC." (PMID 32265595, 2020). "C-type lectin domain family 3 member B (CLEC3B) has been reported in various cancers, but its correlation with lung cancer remains elusive." (PMID 32265595, 2020). "CLEC3B has been reported in a variety of tumors, including hepatocellular carcinoma, ovarian cancer, and lung cancer." (PMID 33134320, 2020). "To further validate the relationship between CLEC3B expression and immune infiltration of lung cancer, we used TIMER to evaluate the correlations of CLEC3B expression with tumor purity and infiltrating levels of immune cells." (PMID 32265595, 2020). "Univariate and multivariate Cox proportional hazards regression models and Kaplan–Meier plots were used to evaluate the prognostic value of CLEC3B in lung cancer." (PMID 32265595, 2020). "Aberrant expression of CLEC3B has been reported in multiple cancers, including hepatocellular carcinoma, ovarian cancer, oral squamous cell carcinoma, and lung cancer." (PMID 32545216, 2020). "Database analysis and patient sample detection revealed that CLEC3B is significantly downregulated in various types of lung cancer." (PMID 32265595, 2020). "The GEO, TCGA and Oncomine databases were analyzed to examine the expression of CLEC3B in lung cancer." (PMID 32265595, 2020). "Our results revealed that CLEC3B is capable of recruiting and regulating immune infiltrating cells in lung cancer." (PMID 32265595, 2020). "Downregulation of CLEC3B was linked to worse OS and PFS in stage 1 to 2, stage T1 to T2 and stage N0 to N1 lung cancer patients (p < 0.05)." (PMID 32265595, 2020). "Patients with a low level of CLEC3B were more likely to present with disease in a late TNM stage, suggesting that CLEC3B is a tumor suppressor gene of lung cancer." (PMID 32265595, 2020). "To examine the expression of CLEC3B in lung cancer, we assessed the published data for cancer and normal tissues from the GEO and TCGA databases." (PMID 32265595, 2020). "It has been reported that the level of CLEC3B is downregulated in stage IA lung cancer, suggesting that CLEC3B could be a useful biomarker for lung cancer diagnosis and prognosis." (PMID 40496615, 2025). "The immunoinfiltration and immunoactivation of lung cancer may also be related to the significant downregulation of CLEC3B." (PMID 39553729, 2024). "High expression of C-type lectin domain family 3 member B (CLEC3B) correlates with favorable OS, which may be linked to immune infiltration and immune activation in lung cancer." (PMID 37187527, 2023). "CLEC3B could be useful biomarkers for early detection of lung cancer and in monitoring its evolution." (PMID 35497520, 2021). "Therefore, the correlation of CLEC3B and immune infiltration levels was evaluated to reveal the possible mechanism by which CLEC3B affects the prognosis of lung cancer." (PMID 32265595, 2020). "CLEC3B was significantly downregulated in stage IA lung cancer patients." (PMID 32265595, 2020). "Our results also suggested that CLEC3B is related to immune infiltration in lung cancer, which may be the mechanism by which CLEC3B affects prognosis." (PMID 32265595, 2020). "Taken together, our results indicate that CLEC3B may improve lung cancer patient prognosis through immune infiltration and immune activation." (PMID 32265595, 2020). "GSEA was used to explore the mechanisms of CLEC3B in lung cancer." (PMID 32265595, 2020). "Thus, our results revealed that the expression of CLEC3B can distinguish lung cancer patients from healthy individuals with high sensitivity and specificity." (PMID 32265595, 2020). "As such, we validated that CLEC3B has prognostic value in lung cancer." (PMID 32265595, 2020).
lung carcinoma (continued). "In addition, the results showed that low expression of CLEC3B predicted poorer PFS than high expression in all lung cancer patients (HR = 0.60, 95% CI 0.49–0.74, p = 8.3e−07), ADC patients (HR = 0.50, 95% CI 0.36–0.69, p = 1.6e−05) and SCC patients (HR = 0.40, 95% CI 0.23–0.67, p = 0.00038)." (PMID 32265595, 2020). "In addition, we also found that CLEC3B may be related to the inhibition of cell proliferation in lung cancer, which is consistent with a report in clear cell renal cell carcinoma." (PMID 32265595, 2020). "Furthermore, our results indicate that CLEC3B is significantly downregulated in stage IA and has great diagnostic value for lung cancer at an early stage, since the AUC value of CLEC3B for the diagnosis of stage IA lung cancer patients was approximately 1, which indicates great significance." (PMID 32265595, 2020). "In addition, several cell cycle-related gene sets were enriched in the CLEC3B low expression group of ADC and SCC, which suggests that CLEC3B may also be involved in the inhibition of cell proliferation in lung cancer." (PMID 32265595, 2020). "In addition, univariate and multivariate analyses indicated that the lower expression of CLEC3B may be defined as a risk factor that affects the OS and DFS of lung cancer patients." (PMID 32265595, 2020). "The candidate protein markers were investigated based on the TCGA database, supplemented by Kaplan-Meier plotter and Oncomine analysis, and then AOC3, CLEC3B, CAT, SEPP1, and HBB were selected as potential candidates for early-stage lung cancer." (PMID 40496615, 2025). "The candidate protein markers (AOC3, CAT, CLEC3B, SEPP1, HBB) and traditional tumor markers (CEA, CYFRA21-1, NSE) were combined to construct screening models for lung cancer by machine learning techniques." (PMID 40496615, 2025). "A total of 6 genes (LYVE1, CLEC3B, FGA, AOC3, HYDIN, and HBB) exhibited differential expressions in the plasma of LUSC and the area of the lesion in lung cancer (including LUAD and LUSC)." (PMID 40496615, 2025). "In conclusion, this study identifies IFI30, RNH1 and CLEC3B, VCAN, IGFBP2, C2, TUBB4B as the proteins secreted by lung carcinoma cells and monocytes respectively as a result of their mutual interaction." (PMID 37784035, 2023). "Our analysis identified four highly significant differentially expressed genes in lung cancer, comprising MIF, CLEC3B, FCN3, and EMCN." (PMID 37359381, 2023). "In this study, we have demonstrated that the lung cancer cell-monocyte cross-talk modulates the secretion of IFI30, RNH1, CLEC3B, VCAN, IGFBP2, C2 and TUBB4B favoring tumor growth and metastasis." (PMID 37784035, 2023). "Our analysis also identified four highly significant differentially expressed genes in lung cancer, namely, MIF, CLEC3B, FCN3, and EMCN." (PMID 37359381, 2023). "Based on these results, seven proteins, CD5L, CLEC3B, SERFINF1, ITIH4, SAA4, SERFINC1, and C20ORF3 (AMAP) were confirmed as being upregulated in EVs and were therefore considered as potential lung cancer biomarkers." (PMID 33808296, 2021). "The expressions of candidate protein markers were dynamically observed at the various phases of lung carcinogenesis, which revealed that AOC3, CAT, CLEC3B, SEPP1, and HBB may be the key molecular markers of early lung cancer lesions." (PMID 40496615, 2025). "The C-type lectin domain family 3 member B (CLEC3B), membrane primary amine oxidase (AOC3), hemoglobin subunit beta (HBB), catalase (CAT), and selenoprotein P (SEPP1) were screened as candidate protein markers for early-stage lung cancer." (PMID 40496615, 2025). "Finally, the screening models for lung cancer were constructed by combining candidate protein markers (AOC3, CAT, CLEC3B, SEPP1, HBB) with tumor markers (CEA, CYFRA21-1, NSE) using machine learning." (PMID 40496615, 2025).
lung carcinoma (continued). "In addition, CLEC3B, ITIH4, SERFINF1, SAA4, SERFINC1, and C20ORF3, whose expression was significantly increased in EVs derived from lung cancer patients, can be included as potential biomarkers." (PMID 33808296, 2021). "As expected, in comparison with matched adjacent nontumor tissues, a significant downregulation of CLEC3B was revealed in lung cancer tissues and CLEC3B expression was downregulated in both ADC and SCC samples." (PMID 32265595, 2020). "CLEC3B is significantly downregulated in lung cancer patients compared with nontumor controls according to database analysis and patient tissue sample detection (p < 0.001)." (PMID 32265595, 2020). "Moreover, the expressions of CLEC3B and HBB were reduced in the lung cancer group." (PMID 40496615, 2025). "Moreover, CLEC3B may promote tumor-induced immune response activation and immune infiltration in SCC and may inhibit the proliferation of lung cancer to play an anticancer role." (PMID 32265595, 2020).
hepatocellular carcinoma (12 papers, 2019 to 2025). A malignant tumor that arises from hepatocytes. "Also noteworthy are the genes SPP2, which encodes a protein of the cystatin superfamily, and CLEC3B, which encodes a lectin type C member 3 of family 3, which is associated with metastasis and tumor invasion in other cancers, such as hepatocellular carcinoma." (PMID 36982287, 2023). "Dai and his team found that the downregulation of exosomes CLEC3B in hepatocellular carcinoma promotes metastasis and angiogenesis through AMPK and VEGF signaling and is a potential therapeutic target for hepatocellular carcinoma." (PMID 35936688, 2022). "Correlation of CLEC3B expression and prognosis in hepatocellular carcinoma patients with different clinicopathological factors via Kaplan–Meier plotter." (PMID 33553242, 2020). "(D) The relative proportion of patients with low CLEC3B expression is increased with the tumor progression in hepatocellular carcinoma (P = 0.006)." (PMID 31477130, 2019). "(A, B) The mRNA and protein level of CLEC3B in different hepatocellular carcinoma cell lines were analyzed by real-time polymerase chain reaction (RT-PCR) (A) and western blot (B)." (PMID 31477130, 2019). "In addition, the expression of CLEC3B was downregulated in some tumor tissues, such as renal cell and hepatocellular carcinomas." (PMID 40496615, 2025). "Similarly, downregulation of CLEC3B was also reported in several other carcinomas including hepatocellular carcinoma and oral squamous cell carcinoma." (PMID 36232952, 2022). "However, the interrelation between CLEC3B gene expression, tumor immunity, and prognosis of patients with hepatocellular carcinoma (HCC) is unclear." (PMID 33553242, 2020). "This study demonstrates that CLEC3B acts as a novel independent prognostic factor, and CLEC3B in exosomes might be a potential therapeutic target for hepatocellular carcinoma." (PMID 31477130, 2019). "However, another study found that CLEC3B in hepatocellular carcinoma could inhibit metastasis and angiogenesis via AMPK and VEGF signals." (PMID 37834257, 2023). "Moreover, CLEC3B has been reported in multiple cancers, including hepatocellular carcinoma, ovarian cancer, and oral squamous cell carcinoma, but a large number of in-depth studies are still needed to elucidate the molecular mechanism and specific function of CLEC3B in cancer progression." (PMID 32265595, 2020). "C-Type Lectin Domain Family 3 Member B (CLEC3B), is down-regulated in serum and tumor tissues in different cancers including hepatocellular carcinoma (HCC)." (PMID 31477130, 2019).
clear cell renal cell carcinoma (7 papers, 2019 to 2025). "The gene acts as an oncogene in colorectal cancer because CLEC3B is secreted by cancer-associated fibroblasts promotes tumor cell migration, whereas it could inhibit clear cell renal cell carcinoma proliferation via mitogen-activated protein kinase (MAPK) pathway." (PMID 31396442, 2019). "In clear cell renal cell carcinoma, CLEC3B expression is downregulated and inhibits cell proliferationthe." (PMID 40529813, 2025). "In clear cell renal cell carcinoma, CLEC3B inhibited tumor growth through mitogen-activated protein kinase pathway." (PMID 39553729, 2024). "CLEC3B is downregulated in clear cell renal cell carcinoma (ccRCC), lung adenocarcinoma (LUAD) and HCC." (PMID 36750831, 2023). "In clear cell renal cell carcinoma, CLEC3B also showed a significant downregulation trend." (PMID 39553729, 2024). "Overexpression of CLEC3B can promote fracture healing, inhibit neuronal apoptosis in Parkinson'sdisease, and inhibit the proliferationof clear cell renal cell carcinoma.Furthermore, some studies revealed that serum levels of CLEC3B were downregulated inpatients with cardiovascular disease." (PMID 32696821, 2020).
colorectal cancer (6 papers, 2011 to 2025). A primary or metastatic malignant neoplasm that affects the colon or rectum. "It was reported that CLEC3B secreted from cancer-associated fibroblasts promotes colorectal cancer progression." (PMID 37834257, 2023). "Contradictorily, a recent study reported that secreted CLEC3B from cancer-associated fibroblast promoted the migration of tumor cells in colorectal cancer." (PMID 31477130, 2019). "Also, in colorectal cancer, significantly shorter survival was found for patients with CLEC3B levels below a cut-off point of compared to patients with levels above." (PMID 22091389, 2011).